LRIG2 (leucine rich repeats and immunoglobulin like domains 2)
Diseases named in the same sentence as LRIG2 in open-access papers (continued):
Sharing a sentence is not in itself a finding about the gene and the disease.
lung cancer (4 papers, 2019 to 2022). A malignant neoplasm involving the lung.
endometrial adenocarcinoma (3 papers, 2018 to 2021). "Further molecular investigations to decipher the mechanisms underlying LRIG2 downregulation in endometrial adenocarcinoma are needed." (PMID 29358688, 2018). "Endometrial adenocarcinoma tissues expressed significantly lower levels of LRIG2 mRNA than controls." (PMID 29358688, 2018). "This study also revealed that measuring the LRIG2 expression levels can serve as a useful pre-screening molecular biomarker for accurate diagnosis of endometrial adenocarcinoma." (PMID 29358688, 2018). "In this study, we found that LRIG2 is highly downregulated in endometrial adenocarcinoma patients and that it functions as a tumor suppressor." (PMID 29358688, 2018). "To determine cellular functions of LRIG2, we performed cell-viability assays using endometrial adenocarcinoma cell lines." (PMID 29358688, 2018). "LRIG2 also inhibited proliferation of the Hec-1A and Ishikawa endometrial adenocarcinoma cells by upregulating p21." (PMID 29358688, 2018). "In this study, we demonstrate, for the first time, that LRIG2, a previously unreported growth suppressor, inhibits the growth of endometrial adenocarcinoma by inducing apoptosis and inhibiting cell proliferation." (PMID 29358688, 2018). "Besides, Dae-Shik Suh and his colleagues reported that LRIG2 was a tumor suppressor gene in endometrial adenocarcinoma and inhibited cell growth through regulating PI3K/AKT and EGFR." (PMID 32863771, 2020). "Thus, our results demonstrated that LRIG2 is a growth suppressor of endometrial adenocarcinoma cells." (PMID 29358688, 2018). "Here, we identified, for the first time, that LRIG2 is downregulated in endometrial adenocarcinoma tissues of patients and functions as a growth suppressor by promoting apoptotic cell death and cell-cycle arrest in Hec-1A and Ishikawa endometrial carcinoma cells." (PMID 29358688, 2018). "Moreover, we report that LRIG2 is downregulated in endometrial adenocarcinoma tissues of patients." (PMID 29358688, 2018). "Although LRIG2 has been shown to be highly downregulated in endometrial adenocarcinoma cell lines, the present study did not identify any prognostic role of LRIG2 expression in EC." (PMID 33802837, 2021). "Furthermore, elucidation of the detailed mechanistic events by which LRIG2 acts as a novel upstream regulator of PI3K/AKT and EGFR in endometrial adenocarcinoma is needed." (PMID 29358688, 2018).
endometrial cancer (3 papers, 2018 to 2022). Primary or metastatic malignant neoplasm involving the endometrium (mucous membrane that lines the endometrial cavity). "LRIG2 was expressed in both the membrane and cytosolic fractions of endometrial cancer cells and caused release of mitochondrial cytochrome c into the cytosol, indicating that LRIG2-induced mitochondrial apoptosis." (PMID 29358688, 2018). "In endometrial cancer, LRIG2 promotes the expression of anti-apoptotic proteins and inhibits the expression of pro-apoptotic protein." (PMID 36183058, 2022). "Ectopic expression of LRIG2 downregulated the pro-survival BCL-2 family members, including MCL-1, BCL-xL, BCL2A1, and BCL-2, whereas the pro-apoptotic BCL-2 family members, such as BAK, BAX, and BAD, were upregulated by LRIG2 in endometrial cancer cells." (PMID 29358688, 2018). "We observed that PI3K/AKT and EGFR serve as key kinases that have roles as growth suppressors of Hec-1A endometrial cancer cells by mediating the LRIG2-induced modulation of the BCL-2 family of proteins and p21." (PMID 29358688, 2018). "We also assessed the effect of LRIG2 on cell-cycle progression in endometrial carcinoma cells using flow cytometry." (PMID 29358688, 2018). "Accordingly, our data indicate that LRIG2 acts as a tumor suppressor in endometrial cancer." (PMID 29358688, 2018). "Especially, inhibition of LRIG2-induced cell death by ectopic expression of MCL-1 or by depletion of either BAK or BAX further support our conclusion that LRIG2 induces apoptosis in Hec-1A endometrial carcinoma cells by regulating the delicate equilibrium among the BCL-2 family of proteins." (PMID 29358688, 2018). "In addition, we confirm that endogenously expressed LRIG2 and EGFR proteins are associated in endometrial carcinoma cells, whereas LRIG2 does not regulate EGFR mRNA expression." (PMID 29358688, 2018).
hepatocellular carcinoma (3 papers, 2020 to 2021). A malignant tumor that arises from hepatocytes. "Several studies confirmed that LRIG2 exerted the value of prognosis in diverse types of human cancers, including non-small cell lung cancer, uterine cervical cancer, and hepatocellular carcinoma." (PMID 32863771, 2020).
non-small cell lung carcinoma (3 papers, 2014 to 2020). A group of at least three distinct histological types of lung cancer, including non-small cell squamous cell carcinoma, adenocarcinoma, and large cell carcinoma. "For non-small cell lung cancer, the lncRNA-PCAT-1/miR-149-5p/LRIG2 axis plays a key role to regulate its progression." (PMID 31956374, 2020). "The human leucine-rich repeats and immunoglobulin-like domains 2 (LRIG2) protein has been shown to be of prognostic value in several types of human cancer, however, the expression profiles of LRIG2 have not been described in non-small cell lung cancer (NSCLC)." (PMID 25013483, 2014).
skin cancer (3 papers, 2019 to 2022). "In summary, these data indicate that during tumorigenesis LRIG2 increases skin tumor progression, associated with activation of EGFR/ERBB4‐MAPK signaling." (PMID 31580518, 2019). "In human skin, LRIG2 is expressed in the HF and in the basal layer of the epidermis, and our preliminary data indicate that its expression is increased in skin cancer cell lines." (PMID 31580518, 2019). "Previously, we have shown that LRIG2 acts as an oncogene in skin cancer affecting ERBB signaling." (PMID 33786987, 2021).
squamous cell carcinoma (3 papers, 2013 to 2019). A carcinoma arising from squamous epithelial cells. "LRIG2 was identified to be up‐regulated in various types of squamous cell carcinoma (SCC), but little is known about LRIG2 in cutaneous SCC (cSCC)." (PMID 31580518, 2019). "For instance, Lrig2 expression can be increased in some human tumors, and a combination of high levels of Lrig2 and low levels of Lrig1 correlates with a poor prognosis for a type of early-stage squamous cell carcinoma." (PMID 24086156, 2013).
bladder disease (2 papers, 2019 to 2023). "The novel mouse studies we report here, which point to mainly neurogenic functional defects, support the overall idea that biallelic LRIG2 variants lead to human bladder disease through autonomic neural defects that perturb bladder function." (PMID 37441484, 2023). "Our observations provide strong evidence that a peripheral neuropathy is part of the pathobiology of UFS bladder disease, whether caused by HPSE2 or LRIG2 variants." (PMID 30885509, 2019).
breast carcinoma (2 papers, 2020 to 2021).
cervical carcinoma (2 papers, 2017 to 2021). A carcinoma arising from either the exocervical squamous epithelium or the endocervical glandular epithelium. "In general, high expression of LRIG1 and LRIG3 in tumours is associated with improved survival in cancer patients, whereas high expression of LRIG2 is associated with poor survival even in early-stage cervical cancer patients." (PMID 28841699, 2017). "The expression of the human leucine-rich repeats and immunoglobulin-like domains (LRIG) proteins LRIG1, LRIG2, and LRIG3 has emerged as a new potential prognostic biomarker in different types of human cancer, including cervical cancer." (PMID 28841699, 2017).
neurogenic neurogenic bladder (2 papers, 2016 to 2019). "We also reported compound heterozygous missense LRIG2 variants (p.Arg550Cys in exon 13 and p.Ile852Phe in exon 16) in a patient with a non-neurogenic neurogenic bladder but with a normal smile." (PMID 30885509, 2019).
osteosarcoma (2 papers, 2022 to 2023). A usually aggressive malignant bone-forming mesenchymal neoplasm, predominantly affecting adolescents and young adults. "In this study, we found that LRIG2 was up-regulated in osteosarcoma tissues and cells, and its high expression was associated with Enneking stage and poor prognosis of OS patients." (PMID 36183058, 2022). "LRIG2 acts as an oncogene in osteosarcoma, and it might become a novel target in the treatment of human OS." (PMID 36183058, 2022).
astrocytoma (1 paper, 2014). "By contrast, the protein expression of LRIG2 in the perinuclear area of astrocytoma cells has been found to correlate with improved patient survival." (PMID 25013483, 2014). "LRIG1 has not been associated with improved survival when expressed in the perinulear region, while the protein expression of LRIG2 and LRIG3 in the perinuclear area of astrocytoma cells has been found to correlate with improved patient survival." (PMID 25013483, 2014).
autoimmune disease (1 paper, 2015). A disorder resulting from loss of function or tissue destruction of an organ or multiple organs, arising from humoral or cellular immune responses of the individual to their own tissue constituents. "At least seven of these are involved in autoimmune diseases or immune cell function: Ptpn22, Adora3, Rbm15, Lrig2, Cd53, Nras, and a cluster of six chitinase-like genes." (PMID 26438525, 2015).
cervical intraepithelial neoplasia (1 paper, 2014). "LRIG2 expression was also found in the precancerous cervical epithelium and shown to increase with increasing cervical intraepithelial neoplasia grade." (PMID 25013483, 2014).
chronic kidney disease (1 paper, 2019). Impairment of the renal function secondary to chronic kidney damage persisting for three or more months. "In a sample of 155 children with chronic kidney disease and urinary symptoms, we discovered novel homozygous missense LRIG2 variants that were predicted to be pathogenic in 2 individuals with non-syndromic bladder outlet obstruction." (PMID 30885509, 2019).
endometrial tumor (1 paper, 2018). "In vivo delivery of antisense DNAs against LRIG2 promoted the Hec-1A endometrial tumor growth in a xenograft mouse model, and immunoblotting of these tumor extracts showed consistent modulation of AKT, EGFR, the BCL-2 family members, and p21." (PMID 29358688, 2018). "However, our results revealed that phospho-activation of the PI3K and EGFR pathways by LRIG2 contributes to inhibition of endometrial tumor growth, implying a non-canonical role for PI3K/AKT in opposing cell survival and proliferation." (PMID 29358688, 2018).
esophageal carcinoma (1 paper, 2014). A primary or metastatic malignant neoplasm involving the esophagus. "In esophageal carcinoma, a trend towards decreased survival was found for the high expression of LRIG2, however, this trend was not statistically significant." (PMID 25013483, 2014).
neuroblastoma (1 paper, 2024). Neuroblastoma (NB) is the most common solid, extracranial childhood tumor. "To this end, we utilized CRISPR gene editing to excise the LRIG2 SVA in the established SH-SY5Y neuroblastoma cell line and examined LRIG2 transcription and nearby methylation." (PMID 38191889, 2024). "We noted that LRIG2 SVA dosage was associated with contrasting effects on PPM1J expression in our ΔSVA SH-SY5Y cell lines and in the NABEC data, and postulate that this may be due to phenotypic differences between SH-SY5Y neuroblastoma cells and the frontal cortex tissue collected in NABEC samples." (PMID 38191889, 2024).
pituitary adenoma (1 paper, 2014). "As for pituitary adenoma, LRIG2 expression has been found to predict the invasiveness of pituitary tumors and a poor prognosis." (PMID 25013483, 2014).
sarcoma (1 paper, 2022). A usually aggressive malignant neoplasm of the soft tissue or bone. "Kaplan–Meier survival curves of OS based on LRIG2 expression using the online bioinformatics tool GEPIA2, and the results indicated that there was a correlation between the expression of LRIG2 and the overall survival of sarcoma patients." (PMID 36183058, 2022).
tumor (18 papers, 2012 to 2025). "It was reported that the expression of LRIG1 was negatively correlated with tumor grade and associated with better survival in numerous tumors, which indicated that the functions of LRIG2 and LRIG1 were different in the progression of tumors." (PMID 36183058, 2022). "However, protein levels of LRIG2, which has been more implicated as tumor promoter, were also elevated." (PMID 41201961, 2025). "The same applies to Lrig2 that has been implicated in tumor biology." (PMID 30885509, 2019). "We also describe the signaling pathways underlying the tumor-suppressive effects of LRIG2." (PMID 29358688, 2018). "An association was also found between the expression of LRIG2 and specific tumor markers." (PMID 25013483, 2014). "LRIG2 enhances tumor growth in diverse tissues, including brain and skin, a property conferred in part by modulating growth factor signaling." (PMID 37441484, 2023). "Hoesl’s analysis of transgenic mice overexpressing LRIG2 showed protein changes in the EGF/ERBB system as well as increased tumor progression with a more rapid development of cSCC-like phenotype." (PMID 35956111, 2022). "Of note, cell biology experiments implicate LRIG2 in axon guidance and in controlling cell turnover in neural tumour cells." (PMID 35812751, 2022). "Previous studies revealed that LRIG2 was abnormally over-expressed in a number of tumors and promoted tumor progression." (PMID 36183058, 2022). "While LRIG1 and LRIG3 are thought to be tumor suppressors, LRIG2 expression is mostly related to poor prognosis." (PMID 33786987, 2021). "Altogether, our data suggest that LRIG2 has a tumor promoting function in murine skin, which results in an accelerated onset of cSCC development." (PMID 31580518, 2019). "LRIG1 and LRIG3 show mostly tumor‐suppressive function, whereas LRIG2 frequently seems to act as an oncoprotein." (PMID 31580518, 2019). "Instead of papillomata, LRIG2‐TG mice developed a cSCC‐like phenotype on their backs, which started 6 weeks after tumor initiation." (PMID 31580518, 2019). "Our findings during early hyperproliferative stages point to a tumor‐promoting influence of LRIG2 excess." (PMID 31580518, 2019). "When homeostasis was disrupted, the overexpression of LRIG2, however, resulted in increased inflammation, angiogenesis, tumor progression, and an early onset of cSCC, which affected the ERBB signaling and components of the extracellular matrix (ECM)." (PMID 31580518, 2019). "LRIG2‐TG mice showed increased inflammatory cell infiltration and neovascularization, which can be an indication for tumor promotion and progression." (PMID 31580518, 2019). "All cSCC samples (10 cSCC samples/10 LRIG2 positive cSCC samples) revealed prominent LRIG2 expression in tumor cells with a predominantly nuclear staining pattern." (PMID 31580518, 2019). "The leucine-rich repeats and immunoglobuline-like domains (LRIG)-1 protein functions as a tumour suppressor, but less is known about the functions of LRIG2 and LRIG3." (PMID 28841699, 2017). "The LRIG1 is a negative regulator of growth factor signaling functioning as a tumor suppressor in mice models whereas the function of LRIG2 and LRIG3 are less well defined." (PMID 25653716, 2015). "Multivariate analysis was conducted using the Cox proportional hazards model to examine the impact of LRIG2 expression and other clinicopathological parameters, including tumor differentiation status and tumor stage." (PMID 25013483, 2014). "Consistent with the cell-based in vitro studies, tumor growth of LRIG2 and LRIG2ecto overexpression groups were strikingly promoted compared to the control group (**P<0.01)." (PMID 25353163, 2014). "The results showed that the mRNA expression of LRIG2 was decreased in NSCLC cancer tissues, which was associated with histological subtypes and tumor differentiation status." (PMID 25013483, 2014).